KIF19 (kinesin family member 19)
Description:
Plus end-directed microtubule-dependent motor protein that regulates the length of motile cilia by mediating depolymerization of microtubules at ciliary tips.
Synonyms: FLJ37300; KIF19A
Tractability: Antibody: the Human Protein Atlas places it where antibodies can reach.
Gene: Protein-coding gene on chromosome 17 (74,326,188 to 74,355,835, forward strand). Ensembl gene ENSG00000196169.
Subcellular location: Cytoplasm, cytoskeleton; Cell projection, cilium
Subcellular location (Human Protein Atlas): Plasma membrane; Actin filaments; Centrosome
Pathways (Reactome):
Hemostasis: Kinesins
Vesicle-mediated transport: COPI-dependent Golgi-to-ER retrograde traffic
Gene Ontology:
Molecular function: plus-end-directed microtubule motor activity; ATP binding; microtubule binding; microtubule motor activity
Biological process: axonemal microtubule depolymerization; plus-end specific microtubule depolymerization; microtubule-based movement
Cellular component: cilium; kinesin complex; axoneme; cytoskeleton
Genetic constraint (gnomAD): Loss-of-function variants: 98 observed, 92.35 expected, observed/expected ratio (o/e) 1.06, 90% interval 0.9 to 1.25. The upper end of that interval is the gene's LOEUF score, 1.25, which puts it in group 5 of 6, group 1 being the genes least tolerant of losing a copy. Missense variants: 1,373 observed, 1,344.4 expected, observed/expected ratio (o/e) 1.02, 90% interval 0.98 to 1.07. Synonymous variants: 516 observed, 537.55 expected, observed/expected ratio (o/e) 0.96, 90% interval 0.89 to 1.03.
Homologues: Orthologues: chimpanzee KIF19 (98% identical), macaque KIF19 (96% identical), dog KIF19 (90% identical), mouse Kif19a (90% identical), pig KIF19 (90% identical), rat Kif19 (89% identical), rabbit KIF19 (75% identical), guinea pig KIF19 (73% identical), tropical clawed frog kif19 (65% identical), zebrafish kif19 (59% identical). Paralogues in human: KIF21A (24% identical), KIF21B (24% identical), KIF7 (24% identical), KIF1A (23% identical), KIF13B (22% identical), KIF1B (22% identical), KIF13A (21% identical), KIF4A (21% identical), KIF4B (21% identical), KIF11 (21% identical), KIF18A (21% identical), KIF27 (21% identical), and 29 more.
Diseases named in the same sentence as KIF19 in open-access papers:
KIF19 is named in the same sentence as 14 diseases in open-access papers, as found by Europe PMC text mining. Sharing a sentence is not in itself a finding about the gene and the disease. The quoted sentences say what the papers report.
female infertility (3 papers, 2016 to 2024). Diminished or absent ability of a female to achieve conception. "In addition, a mouse KIF19 ortholog is associated with ovarian development and folliculogenesis, and female infertility is reported in Kif19a knockout mice." (PMID 29053721, 2017).
COVID-19 (1 paper, 2025). A disease caused by infection with severe acute respiratory syndrome coronavirus 2. "We identified four variants associated with COVID-19 severity with genome-wide significance (rs58027632 in KIF19; rs736962 in HTRA1; rs77927946 in DMBT1; and rs115020813 in LINC01283)." (PMID 40149929, 2025). "Although additional research studying the functional role of the SNPs in KIF19 is needed, this SNP may contribute to the severity of COVID-19 by impairing correct cilia function, which is essential for removing the virus from the respiratory tract." (PMID 40149929, 2025).
diabetes (1 paper, 2024). "IGLJ3, DNASE1L3, ABCG1, DPEP2, and KIF19 are highly differentiated genes associated with diabetes and periodontitis." (PMID 38532421, 2024). "DPEP2, KIF19 induced diabetes associated with obesity and showing strong interactions with periodontal disease." (PMID 38532421, 2024).
KIF19 also shares sentences with these, for which no sentence is quoted: tumor (2 papers); autism (1); cancer (1); ciliopathy (1); glioma (1); Hydrocephalus (1); neurological disorders (1); Obesity (1); periodontal disease (1); periodontitis (1); schizophrenia (1).